NBAT1 (neuroblastoma associated transcript 1)
Diseases named in the same sentence as NBAT1 in open-access papers (continued):
Sharing a sentence is not in itself a finding about the gene and the disease.
bladder cancer (1 paper, 2021). "While in bladder cancer cells, lncRNA NBAT1 could regulate SOCS6 expression via miR-21-5p." (PMID 34895274, 2021).
chromophobe renal cell carcinoma (1 paper, 2015). Chromophobe renal cell carcinoma is a rare subtype of renal cell carcinoma, originating from the intercalating cells of the collecting ducts and macroscopically manifesting as a well-circumscribed, highly lobulated, solid tumor that is usually diagnosed at an early stage. "Our data showed that NBAT1 was down-regulated in invasive breast cancer, lung squamous cell carcinoma and adenocarcinoma, hepatic cell carcinoma, chromophobe renal cell carcinoma than in normal tissues." (PMID 26378045, 2015).
colorectal carcinoma (1 paper, 2024). A malignant epithelial neoplasm that arises from the colon or rectum and invades through the muscularis mucosa into the submucosa. "In colorectal carcinoma (CRC), Chen Li proved the inhibition effect of lncRNA NBAT-1 on the development of OXA-resistant CRC cells by suppressing miR-4504 to mediate the WWC3/LATS1/YAP axis." (PMID 38243168, 2024).
gastric tumors (1 paper, 2018). "Consistent with our results, we also found overexpression of lncRNAs such as H19, GAS5, TUG1, AP5M1 and MALAT1 and downregulation of LINCROR, POU3F3, HOTAIR, FALEC, NBAT1, and ZEB2-AS1 lncRNAs in TCGA gastric tumor datasets." (PMID 29719612, 2018).
leukemia (1 paper, 2024). A malignant (clonal) hematologic disorder, involving hematopoietic stem cells and characterized by the presence of primitive or atypical myeloid or lymphoid cells in the bone marrow and the blood. "On the contrary, m6A on lncRNA NBAT1 blocks the interaction between an oncogene and its regulator, m6A on rRNA activates the ribosome and promotes tumor suppressor gene transcription, and m6A on mtRNA can inhibit leukemia cell growth through the RMRP-YBX1-TGF-βR1-SMAD axis." (PMID 39497033, 2024).
Stroke (1 paper, 2022). Sudden impairment of blood flow to a part of the brain due to occlusion or rupture of an artery to the brain. "The current study aimed to estimate the levels of four ncRNAs: TUG1 and its target miR-21, NBAT1, and miR-335 to determine their potential use as diagnostic and prognostic biomarkers in AIS patients and their possible relation to stroke-related risk factors and the patient’s thyroid profile." (PMID 36250025, 2022).
tumor (33 papers, 2015 to 2025). "They evidenced that the downregulation of the lncRNA NKILA and NBAT1 are linked to tumor size, whereas the blood concentration of H19 and SPRY4-IT1 is a good parameter to discriminate between BC patients and controls." (PMID 37958880, 2023). "Neuroblastoma associated transcript‐1 (NBAT1) behaved as a tumor‐suppressor and down regulated in invasive breast cancer." (PMID 36274054, 2023). "The lncRNA NBAT1 (neuroblastoma-associated transcript 1), is recognized as a tumor suppressor lncRNA in some cancers." (PMID 35755302, 2022). "For instance, NBAT1 is a potential tumor suppressor, and its higher expression is associated with good clinical outcomes in cancers such as NSCLC, oesophageal cancer, HCC, renal cell carcinoma, and breast cancer." (PMID 36230680, 2022). "Loss of NBAT1 induces tumor cell proliferation, differentiation, migration, and invasion through interaction with EZH2 and miR-21, or targeting ERK1/2- and AKT-mediated signaling pathway." (PMID 34759954, 2021). "In xenograft models, overexpression of NBAT1 is associated with lower tumor volumes and slow growth, whilst NBAT1-silencing results in enhanced tumor growth." (PMID 29657304, 2018). "CASC15 acts as a tumour suppressor and is associated with advanced tumour stages and poor patient survival, while NBAT1 seems to negatively regulate transcription factor NRSF (neuron restrictive silencing factor)." (PMID 27233618, 2016). "Long noncoding RNA—NBAT-1 (Neuroblastoma Associated Transcript 1)—has been found to epigenetically down-regulate tumorigenic factors and promote differentiation of tumor cells." (PMID 28035989, 2016). "In addition to LINC01510, downregulation of lncRNA neuroblastoma-associated transcript 1 (NBAT1) was reported in patients with RCC which is negatively associated with tumor growth and aggressiveness." (PMID 36483915, 2022). "Moreover, overexpression of NBAT1 in high-risk NB cell lines is able to induce differentiation of tumour cells, thus underscoring its requirement for efficient differentiation of neural precursors in NBs." (PMID 26087192, 2015). "There is an aberrant expression of NBAT-1 in various human cancers, which was proven to limit the proliferation, invasion, and metastasis of tumour cells via multiple approaches." (PMID 38243168, 2024). "The depletion of NBAT1 accelerates tumor cell replication and invasion, while excessive NBAT1 expression suppresses these events and tumor cell migration by inhibiting the effects of miR-21 and impacting its targeted gene." (PMID 39015175, 2024). "It was shown that the expression levels of NKILA, and NBAT1 lncRNAs were related to tumor size, and BC040587 expression level related to age, node metastasis, tumor size, and grade (p < .05)." (PMID 36274054, 2023). "NBAT1, another tumor suppressor lncRNA, exerts its activity through the regulation of SOX7 expression." (PMID 37047365, 2023). "Up-regulated tumor-promoting lncRNAs such as MALAT1, UCA1, H19, HIF1A-AS2 and down-regulated tumor suppressor lncRNAs such as NBAT1, GASS, RNCR3, etc., all of which play an important role in the formation and malignant progression of gliomas." (PMID 37153654, 2023). "NBAT1 exerts its tumour suppressive activity by epigenetic silencing of genes such as SOX9, VCAN, and OSMR via its association with chromatin repressor, EZH2." (PMID 36230680, 2022). "Of note, the isoform CASC15-003 shares common biological pathways with NBAT1 in promoting tumor suppression and inducing neuronal differentiation." (PMID 36230680, 2022). "NBAT1 down-regulation correlates with proliferation ability, tumor size, degree of malignancy and cell viability." (PMID 33634032, 2020).
tumor (continued). "Neuroblastoma associated transcript-1 (NBAT-1) is an epigenetic regulator that interacts with EZH2, and functions as a tumor suppressor due to its important role in neuronal differentiation." (PMID 31616462, 2019). "A mechanistic study was able to demonstrate that NBAT-1 acts as a tumor suppressor by interacting with EZH2, a subunit of the global gene expression regulator PRC2 complex." (PMID 27608009, 2016). "Expression analysis of NBAT1 in two independent cohorts (93 and 498) of NB tumours revealed that patients with lower expression of NBAT1 are associated with poor clinical outcome and decreased overall and event free survival." (PMID 26087192, 2015). "Higher levels of NBAT1 in low-risk tumours enable its interaction with EZH2 and subsequent recruitment to the NBAT1 target gene promoters." (PMID 26087192, 2015). "NBAT1 regulates biological processes that are highly critical for tumor development, such as cell proliferation and invasion by associating with PRC2 member, EZH2." (PMID 25859549, 2015). "The role of NBAT1 as an effective tumor suppressor of neurobastomas complements its very important functions during neural lineage differentiation." (PMID 25859549, 2015). "Our study has demonstrated that NBAT1 expression was down-regulated in multiple cancer types, suggesting that NBAT1 was a potential tumor-suppressor gene." (PMID 26378045, 2015). "For nervous system, NBAT1 affects the biological behaviour of tumours through different pathways." (PMID 38243168, 2024). "NBAT1 could suppress metastasis and control tumor progression by regulating cell proliferation and neuronal differentiation." (PMID 35392434, 2022). "Therefore, in the light of all these observations, NBAT-1 and its downstream effectors, involved in tumor suppressor and neuron differentiation activities, can be considered as potential therapeutic targets." (PMID 33921816, 2021). "In clinical practice, NBAT1-mimics could serve as therapeutic agents to reduce tumor growth and progression." (PMID 29657304, 2018). "Interestingly, NBAT1 interaction with PRC2 controls tumor progression by suppressing oncogenes such as SOX9, VCAN, and OSMR." (PMID 29443889, 2018). "Also, NBAT1 shows lower expression in all high-risk tumours including both the MYCN and 11q-subtypes, which constitute a major fraction of high-risk NB tumours." (PMID 26087192, 2015). "Mechanistic study has shown that NBAT1 might exhibit this tumor-suppressing function by modulating the global gene expression regulator PRC2 complex." (PMID 26378045, 2015). "Furthermore, a low expression of NBAT1 is associated with poorer prognosis in NSCLC patients, suggesting that NBAT1 could act as a potential tumor suppressor." (PMID 40723840, 2025). "These lncRNAs (e.g. CADM1-AS1 and NBAT-1) may function as tumor suppressors in ccRCC." (PMID 27494890, 2017). "NBAT1’s sense counterpart CASC15 has several isoforms and among which CASC15-003 and CASC15-004 have been shown to display tumor suppressor functions." (PMID 36230680, 2022). "Five lncRNAs were differentially expressed only in tumors with LNM; however, the fold change between tumor and normal was only significantly greater among LNM-positive tumors for NBAT1, RP11-815J21.4, and RP11-106D4." (PMID 36231143, 2022). "A total of nine studies have found a link between tumour size and NBAT-1 expression, with no statistically significant heterogeneity (P = 0.02, I2 = 55.70%)." (PMID 38243168, 2024).
cancer (20 papers, 2015 to 2025). A tumor composed of atypical neoplastic, often pleomorphic cells that invade other tissues. "It is interesting to highlight that the genes located in this locus, CASC15 and NBAT1, promote differentiation through the regulation of cancer-associated genes." (PMID 33921816, 2021). "NBAT1 also has the potential to serve as a prognostic/diagnostic marker for different types of cancer." (PMID 32100288, 2020). "Eleven studies, which involved 1531 patients were analysed to assess the impact of NBAT-1 expression on OS in multiple kinds of cancers." (PMID 38243168, 2024). "Reduced expression of NBAT-1 can predict poor prognosis in several cancers, as found in the meta-analysis, demonstrating that NBAT-1 can serve as a promising prognostic factor of human cancers." (PMID 38243168, 2024). "This meta-analysis in human cancers was about how the expression level of NBAT-1 influences pathological attributes." (PMID 38243168, 2024). "Cancer patients with high NBAT‐1 expression have been associated with good prognosis, whereas patients with low NBAT‐1 expression have been associated with poor prognosis." (PMID 32100288, 2020). "NBAT‐1 is a well‐studied lncRNA with a defined role in cancer, the mechanism of action for which has recently been elucidated." (PMID 32100288, 2020). "It is proved that aberrant NBAT-1 expressions are likely to affect human cancer prognosis." (PMID 38243168, 2024). "Thus, a quantitative meta-analysis was performed to elucidate the prognostic value of lncRNA NBAT-1 expression in cancer patients." (PMID 38243168, 2024). "Interestingly, we identified NBAT1, a tumor suppressor gene in other cancer types, in the LNM module." (PMID 36231143, 2022). "Previous studies have demonstrated that protein ubiquitination could be regulated by aberrant expression of lncRNAs in human cancers, such as NBAT1, lnc-UICC and OCC-1." (PMID 31592114, 2019). "Later on, NBAT1 was found downregulated in various types of cancer." (PMID 29443889, 2018). "Here, we report that NBAT1 is down-regulated in various types of cancer." (PMID 26378045, 2015). "As discovered in this meta-analysis, reduced expression of NBAT-1 can predict poor prognosis in several cancers, demonstrating that NBAT-1 can serve as a promising prognostic factor of human cancers." (PMID 38243168, 2024). "In addition to HOTAIR, other lncRNAs, such as neuroblastoma associated transcript 1 (NBAT1, also known as CASC14), LINC-PINT (also known as MKLN1-AS1) and MIR31 host gene (MIR31HG) have been shown to interact with PRC2 to influence the epigenetic state of cancer cells." (PMID 29443889, 2018). "However, the roles of NBAT1 in other cancers remain unknown." (PMID 26378045, 2015).
NBAT1 also shares sentences with these, for which no sentence is quoted: adenocarcinoma (1 paper); cervical cancer (1); endometrial cancer (1); invasive breast carcinoma (1); ischemic stroke (1); lung carcinoma (1); lung squamous cell carcinoma (1); metastatic disease (1); non-small cell lung carcinoma (1); oesophageal cancer (1); psoriasis (1); renal cell carcinoma (1).